MMP14 (matrix metallopeptidase 14)
Diseases named in the same sentence as MMP14 in open-access papers (continued):
Sharing a sentence is not in itself a finding about the gene and the disease.
tumor (continued). "Other mouse models of epithelial cancers have also identified MMP14 expression, particularly in tumor-associated cells of the TME, to be involved in cancer progression." (PMID 31466240, 2019). "Previous studies and our microarray data showed that MMP14 expression is upregulated in ESCC tumor tissues and is associated with a poor prognosis, findings that are attributable at least in part to the metastasis-promotion function of MMP14 in ESCC cells." (PMID 29379981, 2018). "MMP-14 also activates other pro MMPs such as proMMP-2/-9/-13, and through combined activities these MMPs cause effective tissue degradation and enhance tumor invasion and metastasis." (PMID 30034628, 2018). "MMP-14 expression is elevated in most human cancers, and is associated with tumor invasion and metastasis." (PMID 28827574, 2017). "The data presented here identify, for the first time, a role of CAIX in promoting tumor cell invasion through a strong association with MMP14, and regulating MMP14-mediated type I collagen-degradation activity." (PMID 28692057, 2017). "Taken together, the association of phosphorylated cld7 with integrins, which is accompanied by FAK activation and ezrin association, contributes to tumor cell motility and the association with MMP14 in GEM supports invasiveness." (PMID 25514462, 2015). "Consistent with these evidences that MMP14 and Snail have been implicated in tumor development and progression, our study showed MMP14 and Snail were enriched in the primary GC tissues that inversely correlated to miR-22 levels." (PMID 26610210, 2015). "The firefly luciferase activity normalized to that of Renilla was significantly reduced in the tumor cells stably transfected with miR-337-3p precursor, and the effects were abolished by mutation of miR-337-3p binding site within the MMP-14 promoter." (PMID 26084291, 2015). "PNCA, as an important indicator of tumor proliferation index, is more strongly associated with semaphorin-3A and MMP-14." (PMID 24765144, 2014). "A number of ECM degrading MMPs, such as MMP1, MMP2 and MMP14, have been implicated in the process of tumor invasion and metastasis." (PMID 25349534, 2014). "In this immunohistochemical study the nuclear localization of MMP-14 was associated with aggressive tumor features including poor prognosis." (PMID 19531263, 2009). "In the present study, we found significant associations between the expression of MMP-14 and clinicopathological parameters indicative of tumour aggressiveness." (PMID 17342087, 2007). "Additionally, MMP-14 (also known as MT1-MMP) has been implicated in tumor progression and is closely associated with tumor-associated macrophages (TAMs) in various solid tumors (Niland, Riscanevo & Eble, 2021)." (PMID 40611940, 2025). "Collectively, these findings suggest that while high Maspin expression in early lesions may confer a tumor-suppressive effect, the aberrant nuclear localization of β-catenin and the upregulation of MMP-14 are associated with malignant progression." (PMID 40572725, 2025). "Interestingly, MMP14 showed the strongest association with poor outcomes, emphasizing its aggressive tumor-promoting behavior." (PMID 40604111, 2025). "Cancer-associated fibroblasts expressing MMP14 within the tumor immune microenvironment could be a promising therapeutic option in advancing stage III COAD." (PMID 40264753, 2025). "In addition, according to an ST analysis, high expression of MMP14 has been shown to be associated with tumor progression, poor prognosis, and CAFs and TAMs in tumor tissue." (PMID 39075612, 2024). "An overexpression of MMP-2, MMP-3, MMP-9, and MMP-14 is associated with tumor metastasis." (PMID 38201509, 2023). "Furthermore, in biopsies, MMP14 expression in tumour nests and CAFs and the co-scoring system were associated with ENE + and TME activity-related features, such as DR and TILs." (PMID 36765296, 2023). "Only MMP14 expression in CAFs and the tumour nest was associated with ENE+ (all p < 0.05)." (PMID 36765296, 2023).
tumor (continued). "Notably, this study revealed faster tumor growth in MMP-14-deficient tumors than in wild-type tumors, indicating an inhibitory role of MMP-14 in primary tumor growth." (PMID 36741729, 2022). "Similarly, a recent study demonstrated that loss of EC-derived MMP-14 inhibits melanoma growth and metastasis by regulating tumor vessel stability." (PMID 36741729, 2022). "In conclusion, an immune‐related gene prognostic model was constructed, patients with high‐risk scores have poorer survival status, M2‐phenotype tumour‐associated macrophages (TAMs) up‐regulate two immune‐related genes, MMP14 and INHBA, which were used to establish the prognostic model." (PMID 35150061, 2022). "We selected the cases of ADAM17 and MMP14 targets to illustrate the potential of our methodology, as they have been implicated in tumour evasion through metalloproteinase function and catalysis of cleavage of endogenous MHC class I-related chain molecule (MIC) A and B." (PMID 35379165, 2022). "Furthermore, GAMs were capable of augmenting the secretion several genes like Vegfa and Hgf which implicated in angiogenesis, ARG1 and Tgfb3 which are implicated in immune suppression, and MMP2, MMP14, and Ctgf which are implicated in tumor invasion." (PMID 35419058, 2022). "Lastly, TIMP2, MMP2 and MMP14 are mediators of ECM degradation associated with tumor metastasis." (PMID 34140574, 2021). "However, before this study, the underlying roles of MMP14 in tumor immunology and its suitability as a prognostic biomarker for DLBCL were not investigated." (PMID 32974187, 2020). "We further investigated the relationship between MMP14 expression and various immune markers for different immune cells, including monocytes, tumor-associated macrophages (TAMs), M0, M1, and M2 macrophages, neutrophils, and dendritic cells using TIMER and GEPIA." (PMID 32974187, 2020). "In addition, tumor-associated macrophages express MMP14 and are involved in matrix remodeling, as shown in a colorectal cancer orthotopic mouse model." (PMID 31466240, 2019). "After a pipeline of bioinformatics analyses, we identified three tumour-associated factors, namely, matrix metallopeptidase 14 (MMP14), C–X–C motif chemokine ligand 12 and wntless Wnt ligand secretion mediator, which were further confirmed in human BUCC tissues." (PMID 30874539, 2019). "Furthermore, an N-terminal 40 kDa fragment of BAI1, Vstat40, released by the cancer-associated protease matrix metalloproteinase 14 (MMP14), has been reported to suppress tumor angiogenesis and to delay tumor growth in a mouse model of a human tumor xenograft." (PMID 30513696, 2018). "To delineate the Src-FAK-dependent downstream signalling pathways, which may induce the expression of MMP14, we focused on c-Jun, since its expression and phosphorylation transcriptionally regulate MMPs and could be linked with tumour progression." (PMID 26001294, 2017). "Furthermore, MMP14 exhibited significant correlations with immunomodulators, particularly immunostimulants and immunosuppressants, and was associated with immune cell infiltration within tumor tissues." (PMID 40352589, 2025). "In addition, most tumor stromal cells, including tumor associated macrophages, endothelial cells and tumor fibroblasts are known to express MMP-14 and changes in their number within the tumor may have contributed to reduced tumor growth." (PMID 30034628, 2018). "High MMP-14 expression is associated with early death of patients with supraglottic carcinoma, colorectal carcinoma, or breast cancer and is correlated with lymph node metastases, progression, invasion, poor clinical stage, larger tumor size, and with increasing tumor stage." (PMID 21152183, 2011). "MMP‐2 and MMP‐9 are gelatinases involved in collagen degradation, tumour invasion and angiogenesis, while MMP‐14 activates other MMPs and promotes tumour cell migration." (PMID 41546170, 2026).
tumor (continued). "The glial cell expresses versican, an endogenous TLR2 ligand, which significantly increases the expression of matrix metalloproteinase 14 (MMP14) in microglia that promotes the tumor invasiveness and growth." (PMID 41268299, 2025). "The 9th LRR domain of LUM, lumcorin has been shown to be an inhibitor of MMP‐14 and has anti‐tumor activity, has anti‐angiogenic properties and interacts with α2β1 integrin to inhibit micro‐capillary tube formation." (PMID 41376803, 2025). "The findings above were further supported by MMP‐14 western blot analysis on ECM extracts from both tumor models." (PMID 40913457, 2025). "The present in-situ resection experiments indicated that both NIRF and PET imaging with the MMP-14 targeted peptide probes successfully detected residual tumor regions in the surgical cavity during GBM xenograft debulking." (PMID 40093889, 2025). "The present studies assessed the tumor-specific localization and contrast of these MMP-14 targeted peptides relative to 5-ALA in GBM models." (PMID 40093889, 2025). "MMP-14 is a membrane-bound metalloproteinase essential for extracellular matrix degradation and remodeling, which in turn facilitates tumor invasion and metastasis." (PMID 40572725, 2025). "A growing body of evidence indicates a substantial upregulation of MMP14 expression across various tumor types, with an established impact on cellular migration, inflammation, and angiogenesis." (PMID 40352589, 2025). "Our study revealed a correlation between MMP14 expression and various molecules regulating tumor immune cells, including CSF1R, HAVCR2, KDR, PDCD1LG2, TGFB1, CD70, CD86, and CXCL1." (PMID 40352589, 2025). "Intratumoral ASCs also produce tumor-reactive IgG targeting MMP14 in HGSOC, specifically encapsulating tumor cells with high MMP14 expression." (PMID 39744696, 2025). "NIRF signal intensities in the bulk tumor and contralateral normal brain regions correlated with the corresponding MMP-14 immunofluorescence signal observed in U87 and D54 orthotopic xenografts." (PMID 40093889, 2025). "In LUAD, the regulation of MMP14 at mRNA and protein levels can promote tumor progression and induce macrophage M2 polarization." (PMID 40407957, 2025). "In obesity, the tumour-surrounding adipocytes are more prone to activating the HIF-1α/MMP-14 signalling pathway." (PMID 39941741, 2025). "MMP-9 (matrix metalloproteinase-9) and MMP-14 (matrix metalloproteinase-14) drive tumor invasion and growth by degrading extracellular matrix (ECM) proteins." (PMID 39975023, 2025). "The described shift in correlation between PLTP and MMP14 highlights how tumour progression can fundamentally rewire cellular interactions and molecular pathways within the TME." (PMID 40134439, 2025). "The findings suggested that tumor tissue samples exhibited a higher MMP14 fluorescent signal intensity than normal tissue samples." (PMID 40352589, 2025). "Membrane-type MMPs, like MMP-14, can activate pro-MMPs at the cell surface, facilitating pericellular matrix degradation, which is essential for tumor invasion and metastasis." (PMID 40265458, 2025). "To validate this finding from the proteomics analysis, we performed immunofluorescence staining of MMP-14 in both tumor tissues and observed significantly elevated signals colocalizing with the cancer cells in the dECM-tumors in comparison to tumoroids." (PMID 40166338, 2025). "PpIX fluorescence in the bulk tumor and contralateral normal brain weakly correlated with MMP-14 immunofluorescence signals in corresponding brain regions (R2 = 0.29)." (PMID 40093889, 2025). "In contrast, MMP14 remained consistently elevated across primary and metastatic stages, indicating its persistent role in tumor progression and metastasis." (PMID 40604111, 2025). "VEGF (vascular endothelial growth factor) stimulates angiogenesis by interacting with MMP-9 and MMP-14, promoting tumor metastasis." (PMID 39975023, 2025).
tumor (continued). "CD44 ectodomain shedding often occurs at the leading edge of migrating tumor cells, where it forms a complex with MMP14 to facilitate cytoskeletal interactions and tumor invasion." (PMID 41440277, 2025). "Recent studies have demonstrated that MMP-14 catalyzes pericellular collagen lysis, promoting tissue invasion of tumor cells." (PMID 40869275, 2025). "Qualitative and quantitative analyses indicated imaging signals from the MMP-14 targeted peptide probes localized in tumor regions during in situ resection." (PMID 40093889, 2025). "MMP-14 was low-to-moderate in OPMDs but markedly elevated at the invasive fronts of carcinomas, consistent with its function in tumor invasion." (PMID 40572725, 2025). "Low extra-tumor NIRF signals from the MMP-14 targeted peptide probes were observed from gross brain slices of mice bearing either U87 or D54 GBM xenografts." (PMID 40093889, 2025). "The findings demonstrated a significant increase in MMP14 expression in tumor tissues compared to normal tissues." (PMID 40352589, 2025). "To validate the proteomics findings above, taking MMP‐14 as an example we performed immunofluorescence staining in both tumor tissue types." (PMID 40913457, 2025). "MMP14 is elevated in numerous cancers and facilitates tumor angiogenesis, inflammation, and progression." (PMID 40121502, 2025). "Immunohistochemistry (IHC) analysis was performed on normal and tumor tissues from CRC patients to assess MMP14 protein expression." (PMID 40352589, 2025). "Conversely, MMP14 expression exhibited an inverse relationship with tumor proliferation, G2M checkpoint activity, and related processes." (PMID 40352589, 2025). "We examined the potential relationship between MMP14 and tumor-infiltrating immune cells (TIICs) to elucidate the CRC microenvironment and its potential impact on CRC heterogeneity and prognosis." (PMID 40352589, 2025). "We observed significantly elevated MMP‐14 presence colocalizing with tumor cell colonization in dECM‐tumors in comparison to tumoroids, which was localized both intracellularly and at the cell surface, shown by co‐localization with E‐cadherin (E‐Cad)." (PMID 40913457, 2025). "MMP7 and MMP11 showed moderate cytoplasmic staining, while MMP14 exhibited stronger and more diffuse staining, suggesting its prominent role in tumor invasion and extracellular matrix remodeling." (PMID 40604111, 2025). "In contrast, ERBB2, SDC1, and MMP14 exhibited elevated expression levels in the tumor group (All p < 0.05)." (PMID 38189813, 2024). "We found that cysteamine treatment at micromolar concentrations specifically targets MMP2, MMP9, and MMP14, leading to the inhibition of tumor invasion and migration in GBM cells overexpressing these genes." (PMID 38893149, 2024). "In light of the significant role of the BM in tumor progression, our study introduces MMP14 as a pivotal hub gene within the BMRGs cluster impacting BLCA prognosis and response to immunotherapy." (PMID 38898429, 2024). "Our findings suggest that MMP14 expression correlates with immune cell infiltration and immune checkpoint expression, highlighting its dual role in tumor biology and immune landscape modulation." (PMID 38898429, 2024). "Unlike previous studies that focused broadly on MMPs, our study focused on MMP14 and explored its relevance to tumor prognosis and immunotherapy response." (PMID 38898429, 2024). "MMP-13 promotes tumour angiogenesis 16, MMP-7 degrades HB-EGF and E-cadherin in the basement membrane 17, 18, and MMP-14 degrades CD-44 and electron-cadherin in the basement membrane 19, which together play a vital role in tumour invasion." (PMID 38911387, 2024). "Taken together, it appears that the MMP‐14/miR‐150‐5p axis plays a key role in regulating tumour metastasis." (PMID 39466654, 2024). "In summary, our work revealed proangiogenic TAN reprograming by the CRC niche, resulting in MMP14/OPN-dependent promotion of tumor vascularization." (PMID 38329810, 2024).
tumor (continued). "The G2 tumor samples contained 14.87, whilst the control contained 1057 mg of MMP-14/kg of total protein content." (PMID 39125675, 2024). "In the discovery cohort, high MMP-14 levels at BL and PD were correlated with tumor shrinkage and longer progression-free survival (PFS)." (PMID 39199626, 2024). "Tumour-reactive antibodies (TRAs) against MMP14 exist naturally in humans and have good immunotherapeutic effects against tumours." (PMID 38736973, 2024). "In preclinical experiments, highly potent antibodies against MMP-14 catalytic domain were found to be efficient in inhibiting MMP-14-mediated tumor development and metastasis, indicating that targeting MMP-14 is a viable therapeutic approach." (PMID 39769318, 2024). "We also considered the potential cross-reactivity of the MMP-11 antibody with other MMPs, such as MMP2 (gelatinase A), MMP9 (gelatinase B), and MMP14 (membrane-type 1 MMP), which are commonly associated with tumor cells." (PMID 38438841, 2024). "Pharmacological inhibition of TAN trafficking or MMP14 activity effectively reduced tumor vascular density, leading to CRC regression." (PMID 38329810, 2024). "Even lower quantities were found in the G3 tumor, as compared to the control tissue (12.93 vs. 1119.8 mg of MMP-14/kg of total protein content)." (PMID 39125675, 2024). "Based on the results, it can be concluded that MMP-14 is significantly less active in tumor tissue than in control tissue; at the same time, it is also approximately 70 times more active in healthy human kidney samples than MMP-15." (PMID 39125675, 2024). "Supporting the idea that MMP14 inhibition–driven induction of fibrosis led to the observed tumor regression, genetic deletion of MMP14, or allosteric inhibition of the MMP14 PEX domain has been shown to impair collagen degradation, limiting tumor growth." (PMID 38329810, 2024). "MMP-2, MMP-9, and MMP-14 can be upregulated in some types of tumor cells through a hypoxia-inducible factor (HIF)-dependent mechanism." (PMID 39408814, 2024). "Studies utilizing fibrosarcoma and gastric carcinoma cell lines with downregulated expression of MMP14 showed impaired tumor cell migration and invasion." (PMID 36876041, 2023). "For example, lamstatin (NC1), the C-terminal domain of the α5-chain of type IV collagen, inhibits tumor cell migration by suppressing both αvβ3 integrin and MMP-14." (PMID 37298452, 2023). "It utilizes the tubular organization, employing MT1-MMP (MMP-14) or MMP-2 protein to remodel the matrix in favor of tumor cell invasion and metastasis." (PMID 36793444, 2023). "The concordance rate (CR) was highest for MMP14 expression, compared to that of other MMPs (CAFs, 81%, p = 0.11; tumour nest, 81%, p = 0.05; co-expression system, 78%, p < 0.01)." (PMID 36765296, 2023). "Lumican (a small, leucine-rich proteoglycan) binds to MMP-14, selectively inhibits protease activity, and prevents collagen degradation, limiting tumor invasion and progression." (PMID 37298452, 2023). "Additional gene analysis revealed an upregulation of genes related to the tumor invasion, like matrix metalloproteinase 14 (MMP14) or lysyl-oxidase like 2 (LOXL2)." (PMID 37686288, 2023). "(a) H&E images are shown on tumours growing in the ears of mice with the indicated manipulations of MMP14 and CTNNA1." (PMID 36892272, 2023). "In MMP14 over-expressing tumours, these clusters were larger, rounder (as judged by aspect ratio), and further from the tumour." (PMID 36892272, 2023). "Together, these analyses demonstrate that MMP14-driven matrix proteolysis promotes invasion in wide collective units and tumour growth in spatially confined contexts." (PMID 36892272, 2023). "The results of the study revealed that PTC tissues exhibited significantly higher expression levels of MMP-2, MMP-9, and MMP-14 compared to adjacent non-tumor tissues." (PMID 38089632, 2023).